CD33 (CD33 molecule)
Diseases named in the same sentence as CD33 in open-access papers (continued):
Sharing a sentence is not in itself a finding about the gene and the disease.
tumor (continued). "Indeed, we observed enhanced tumor cell lysis when CD117 and CD33 Db-FM were added compared to equimolar concentrations of single agents alone." (PMID 39294295, 2024). "Tumor analysis by flow cytometry showed accumulation of human CD45+ and CD33+ cells." (PMID 39839764, 2024). "In our work, this effect might depend on the levels of target-antigen (CD33 and CD117) expression on the tumor cell surface, as well as on the density of the CAR T-cell ligand, fluorescein, decorating the tumor cell surface." (PMID 39294295, 2024). "Indeed, the targeting of myeloid-lineage associated antigens such as CD33 and CD123 has been impeded by their expression in other tissues (CD33 in liver, CD123 in endothelial cells), which raises issues of on-target off-tumor toxicity." (PMID 38254824, 2024). "Notably, inhibitory SIGLECs, such as CD33, SIGLEC-5, 7, 9, and 10, are upregulated in tumor-infiltrating CD4 and CD8 T cells across various cancer types, contributing to the failure of T cell responses." (PMID 38650859, 2024). "Reduced MFI expression in CD33 CARKR T cells may lead to weakened interactions between CAR T cells and tumor cells, which in turn may affect the ability of CAR T cells to recognize and eliminate target cells effectively." (PMID 38184596, 2024). "Based on these observations, Teppert and coworkers have developed a double-targeting immunotherapy combining CAR and TCR technologies: CAR’TCR-T cells, co-expressing CD33-CAR and a transgenic dNPM1-TCR, showed potent and prolonged anti-tumor activity against NPM1-mutant AMLs." (PMID 39518068, 2024). "CD33 is widely used as a marker for tumor infiltrating myeloid cells, so we collected FFPEs from 28 consecutive pairs of BC patients and performed IHC for CD74 and CD33, respectively." (PMID 36911401, 2023). "PD-L1+CD33 positive cells appear to be enriched in the periphery of MCC tumours and may function to shield the tumour against infiltrating PD-1+ lymphocytes." (PMID 37033972, 2023). "Overall, these cells showed reduced histologic tumor grade, EMT, and metastatic potential, concomitant with lessened immune cell activation, recruitment, and immunocompromised tumor background, with special regard to these features in the CD33+/11b+MDSCs." (PMID 38170015, 2023). "The colocalisation and accumulation of NLRP3 and FATP2 with CD33 in fatty grafts demonstrated that NLRP3 and FATP2 might modulate MDSCs in post-transplant tumour recurrence." (PMID 37916155, 2023). "By administering two different TMs (one RevTM-CD123 and the other RevTM-CD33), the same RevCAR-T cell could be targeted by the TM to a CD123+ or CD33+ tumor cell and, by activating the effector mechanism, lead to its elimination." (PMID 37296906, 2023). "This design allowed the CD33 CAR to target only CD33+ tumor cells without targeting the CD33 marker on healthy myeloid cells." (PMID 36831198, 2023). "PD-L1 is expressed on tumour infiltrating cells expressing CD11c+, CD162+ and CD33+, attributed to DCs and macrophages but some CD33+ cells may be MDSCs." (PMID 37033972, 2023). "In CC, the expression of METTL3 and CD33+ MDSCs in tumor tissues is higher than that in adjacent normal tissues, and their expression is positively correlated." (PMID 36071523, 2022). "More importantly, the reconstituted CD33-knockout HSCT animal models, when challenged with tumor cells, are well tolerated with CD33 CAR-T or ADCs immunotherapy and have no side effects on normal myeloid lineage." (PMID 37193354, 2022). "Overall, these data clearly suggest that CD33-CAR-NK cells might be suitable for the treatment of AML, due to their strong anti-tumor efficacy and highly improved presence in BM, spleen, and PB compared to normal NK cells." (PMID 35418180, 2022). "We also observed activation of Fabrack T cells by CD33 memAb in the absence of targeted tumor cells." (PMID 35728874, 2022).
tumor (continued). "In an MDA-MB-468 heterogeneous tumor comprizing HER2-GFP positive cells and CD33-DsRed cells, time-lapse images clearly demonstrated the specific tumor killing by Fabrack T cells in the presence of a corresponding memAb and capability of Fabrack T cells to eradicate a heterogeneous tumor." (PMID 35728874, 2022). "Incubation of primary AML samples with CD33- or CD123-redirected CAR T cells resulted in a significant upregulation of PD-L1 on AML blasts and the combination of CAR T cells with ICIs increased the anti-tumor effects of CAR T cells." (PMID 34302116, 2022). "Tumor analysis of the PET data using volume of interest (VOI) showed significant blocking of 89Zr-lintuzumab in the group pre-treated with native lintuzumab (pre-blocked group), thus indicating specific targeting of CD33 on OCI-AML3 cells in vivo." (PMID 36235126, 2022). "Our group has also recently observed upregulation of PD-1 and TIM-3 on cytokine-induced killer cells (CIK) expressing a CD33-specific CAR isolated from the BM of tumor-bearing mice nonresponding to the treatment." (PMID 34302116, 2022). "We show that adding rhIL-7-hyFc to CAR T cells improves T cell expansion, persistence, and anti-tumor activity, both with human CAR T cells targeting CD19 or CD33 in an NSG xenograft model and with murine CAR T cells targeting CD19 in two different strains of immunocompetent mice." (PMID 35697686, 2022). "The CD16/IL-15/CD33 TriKE not only was able to enhance NK function against CD33+ cell lines and AML blasts, but also to expand and sustain human NK cells in vivo, reducing tumor burden in a xenograft model." (PMID 35493522, 2022). "CD33-expressing tumor cells were effectively targeted and lysed by anti-E3–anti-CD33 and anti-E3–anti-CD123-activated SAR T cells, but not unt T cells." (PMID 33414484, 2021). "Overall, this study provides critical insights into the pathways affected in tumor-infiltrating myeloid cells during the progression of CRC and their potential contribution to disease progression, and identifies a CD33+ gene signature which predicts poor disease-specific survival in CRC patients." (PMID 33000418, 2021). "The first BiKE in AML targeted CD16 and CD33, and was able to induce NK cell activation against tumor cells regardless of MHC-1 presence and to eliminate AML cells." (PMID 34071099, 2021). "CD8/CD33 ratio implies the infiltrate composed of many CD8+ lymphocytes with low numbers of immunosuppressive CD33+ MDSCs, and hence a better situation to fight the tumor growth." (PMID 33793095, 2021). "We found that sorted tumor-infiltrating CD33high cells expressed high levels of CD33 gene, while lacked gene expression of CD3E, CD8A and NCAM1 (gene for CD56), compared to CD8+ T cells." (PMID 33000418, 2021). "Using immunostaining, we evaluated the expression of CD33, a marker of human MDSCs, in tumor tissues from obese OSCC patients and nonobese patients." (PMID 34650054, 2021). "In order to reduce on-target/off-tumor reactions and to increase the specificity of the RevCAR T-cell response towards AML blasts, we aimed to establish RevCAR T-cells for a programmable combinatorial targeting of AML blasts co-expressing CD33 and CD123." (PMID 34638268, 2021). "We then performed immunohistochemistry to qualify tumor infiltrating immune cells, focusing on leukocytes (CD45+ cells), and T lymphocytes (CD3+), CD8+ T cells, B lymphocytes (CD20+) and myeloid cells (CD33+)." (PMID 33042257, 2020). "BiKE connects a single-chain variable fragment (scFv) to the anti-CD16 recognition site with the scFv of a tumor specific antigen, such as CD19/CD20 for non-Hodgkin lymphomas, CD33/CD123 for acute myelogenous leukemia/AML and CD30 for Hodgkin lymphoma, to enhance NK cell recognition of tumor cells." (PMID 32762681, 2020). "We found that CD33+ cells were heterogeneously distributed and preferentially localized at the tumor stroma rather than the epithelium." (PMID 32092078, 2020).
tumor (continued). "In more detail, SIGLEC17P expression could be used by Tregs to circulate among all tissues; CD33, PCDH1, JAM2, CDHR3, and ITGA3 would orchestrate migration/retention in NI TDLNs; CADM1 in I TDLNS; and CEACAM6 in tumor." (PMID 32601304, 2020). "Cox model analysis revealed that the level of METTL3 in tumour cells was an independent factor for patient survival, specifically for DFS (HR = 3.157, P = 0.022) and OS (HR = 3.271, P = 0.012), while the CD33+ MDSC number was an independent predictor for DFS (HR: 3.958, P = 0.031)." (PMID 33059689, 2020). "Similarly, after adjusting for correlation by tumor purity in TIMER, IGFLR1 expression level was significantly correlated with CD33 (partial cor = 0.61, p < 0.001) and CD11b (partial cor = 0.499, p < 0.001) in ccRCC." (PMID 33324675, 2020). "The non-targeting control Nb showed no tumor accumulation, confirming the specific targeting of anti-CD33 Nbs." (PMID 31906437, 2020). "Interestingly, in patients with advanced-disease stages (II–IV), METTL3 in tumour cells was an independent factor for DFS (HR = 6.725, P = 0.010) and OS (HR = 5.140, P = 0.021), while CD33+ MDSC density was an independent factor for OS (HR = 8.802, P = 0.037)." (PMID 33059689, 2020). "Flow cytometry indicated CD33 expression is higher on M-MDSCs, and CD33+ MDSCs are found in the blood and tumours regardless of cancer subtype." (PMID 31462392, 2019). "Particularly, CD11b+CD33+HLA-DR- MDSCs significantly increase in lung cancer patients after thoracotomy, and are more efficient in secreting MMP-9, promoting angiogenesis and tumor growth than MDSCs isolated before surgical operation in allograft tumor model." (PMID 31477121, 2019). "Our results support the role of CD33 as an inhibitory receptor preferentially regulating the NKG2D/DAP10 cytotoxic signaling pathway, which could be involved in self-tolerance and tumor and infected cell recognition." (PMID 31143782, 2019). "A similar result was obtained when a macrophage signature comprising a subset of eight widely used markers (CD14, CD105, CD11b, CD68, CD93, CD33, IL-4R and CD163) for the mononuclear phagocyte system was used to identify tumours highly infiltrated by macrophages." (PMID 29921315, 2018). "Functioning as an inhibitory receptor expressed on NK cells, Siglec-9, another member of CD33-related Siglecs, has been demonstrated to play a negative role for reactive oxygen species (ROS) production on neutrophils to suppress anti-tumor activity." (PMID 29617289, 2018). "Additionally, alternative surface tumor antigens such as CD20, CD30, CD33, CD123, CD38, CD138, Ig κ light chain and Lewis-Y are accompanied with off-target binding." (PMID 29448937, 2018). "The combination of PD-L1 expression ≥1% tumor cells with a CD8+ density lower than the median (p = 0.002; HR, 4.2; 95% CI, 1.5–12), or with a CD33+ density lower than the median (p = 0.007; HR, 4.7; 95% CI, 1.7–13) identified a subset of LADC patients with poor OS." (PMID 30216999, 2018). "In this study, we found that there were positive correlations between the expression of ST2 and FOXP3, CD11B, and CD33, indicating that the IL-33/ST2 axis may also regulate the function of Tregs and MDSCs in the tumor microenvironment of STS." (PMID 29896199, 2018). "The tumor cells in this case were rather small (< 20 μm) and monotonous and expressed CD33, thereby not fulfilling the morphologic and phenotypic requirements for HS." (PMID 30084011, 2018). "In ongoing clinic trials, the surface tumor antigens CD20, CD30, CD33, CD123, CD38, CD138, Ig κ light chain and Lewis-Y, have been applied as CAR targets, providing a pool of target antigen candidates in cancer treatment, although their clinical outcome remains further determined." (PMID 29448937, 2018). "In contrast to CD68+, CD39 was found only on tumor vasculature, whereas Arginase II and CD33 expression was virtually absent." (PMID 30054667, 2018).
tumor (continued). "In other studies, the antitumor efficacy of bispecific antibody constructs cross-linking HER2 or CD33 with CD3 could also be improved by blocking PD-L1, which is expressed on tumor cells and inhibits T-cell responses via ligation of PD-1." (PMID 27966460, 2017). "The patient's bone marrow cells indicated clonal evolution of the tumor cells expressing CD13dim, CD33+, CD117+, and lacking HLA-DR, CD34 and CD11b." (PMID 27708545, 2016). "However, the frequencies of macrophages that were independently CD33+, CD163+ or CD206hi were significantly lower in tumor compared with NTB." (PMID 27195119, 2016). "Interestingly, these CD33+ and CD11b+ MDSC subsets showed some phenotypic (HLA-DRlow and lineage-) and functional convergence despite preferential induction by different tumor models and predominant expression of either CD33 or CD11b." (PMID 21658270, 2011). "TFPI, as the precursor mRNA of hsa_circ_0057335, has been proved to be closely related to the increased expression of CD33 in CHOL and the decreased expression of TFPI‐2 may inhibit cell migration and tumor invasion, playing an essential role in the carcinogenesis and progression of CHOL." (PMID 40304434, 2025). "By co‐targeting CD70 and CD33, they aimed to address antigen heterogeneity in AML treatment and mitigate systemic toxicity in a preclinical model, while simultaneously redirecting untransduced bystander T cells to CD33‐positive tumour cells to enhance antitumour activity." (PMID 40629902, 2025). "In this study, we characterized the MDSCs of ESCC with CD38 and CD33, verified that AZD4547 could inhibit the recruitment of MDSCs through the CXCL8–CXCR2 axis in tumor tissues of hu-HSC-NOG-EXL mice, and verified the tumor suppressive effect of AZD4547 combined immunotherapy in ESCC." (PMID 40722739, 2025). "For example, the strategy of constructing dual-target CAR in series or parallel to overcome the escape of antigen, Knock out CD33, etc., in targeted blood tumor treatment, or use gene mechanism and other designs in solid tumor treatment to solve the non-target Off-Tumor toxicity." (PMID 40244018, 2025). "Although AdFITC-CAR T-cells and single Db-FM significantly reduced tumor cell infiltration in the BM, the combination of Db-FM proved to be the most effective in reducing AML cells and the most efficient in targeting the double-positive CD33+CD117+ subpopulation." (PMID 39294295, 2024). "Untransduced (UTD) T cells, in both the presence and the absence of rapamycin, exhibited low or undetectable levels of interferon-γ (IFN-γ) release following coculture with CD33+ tumor cells in media with and without rapamycin, reflecting minimal T cell activation." (PMID 38502193, 2024). "Notably, no extra‐tumour toxicity or xenograft‐versus‐host response was demonstrated in experiments using the universal CAR dual‐targeting CD33 and CD123 to lysate AML primary cells and AML cell lines." (PMID 38712978, 2024). "Thus, we developed CD33 CAR constructs overexpressing LCK, ZAP70, C-JUN, C-Fos, and IFN-γ, and that overexpressing IL-15, a cytokine known to potentiate CAR T therapeutic activity in various tumor models, as a control." (PMID 39039086, 2024). "However, CD33-TCRTs have failed to recapitulate the impressive anti-tumor responses seen with CD19- and BCMA-TCRTs and efficacy has been limited." (PMID 39095991, 2024). "In addition to the anti-tumor effects of AMV564 on the clearance of MOLM13CG cells in vivo, similar effects were seen when primary CD33+ human AML cells were engrafted in NSG mice even when the human T cells made up only 2% of the peripheral blood cells and AML cells made up 98%." (PMID 38696390, 2024). "Moreover, we also observed that synergies between Ven/Aza and TCBs are likely independent of the specific tumor target, based on our observations with a CD33-TCB." (PMID 38212534, 2024).
tumor (continued). "The panels were designed to identify cytotoxic T cells (CD8+ GZMB+ CD3+), myeloid-derived suppressor cells (MDSCs) (CD11b+ CD33+ HLA-DR-negative) and B cells (CD20+ CD79a+), as well as a panel with CD3 and FOS to confirm the high expression of FOS in the tumour cells." (PMID 36982943, 2023). "Additionally, the most frequent cell population, which was hematopoietic lin−HLA-DR+ cells, expressed CD11c, CD33, CD141, and CD163, which could indicate that it was a tumor-infiltrating macrophage population." (PMID 37894472, 2023). "The comparison of constructs, including 4-1BB or CD28 costimulatory domains, showed that 4-1BB-based constructs, unlike CD28-based ones, could control the new CD33+ THP1 tumor cells added to the medium after 7 days." (PMID 36761751, 2023). "Similarly, non-transduced NK cells did not kill the tumor cells regardless of CD33 expression due to natural resistance of RS4;11 cells to NK cell-mediated killing." (PMID 35058934, 2021). "Importantly, we found that CD33 and METTL3 co-localized in some tumour-infiltrated immune cells." (PMID 33059689, 2020). "Since former studies have found SIGLEC1 (CD169), SIGLEC2 (CD22), SIGLEC3 (CD33), SIGLEC7, SIGLEC9, and SIGLEC15 expressed by immune cell populations could be manipulated by tumor cells to escape immune surveillance, we focused on the five SIGLEC family members." (PMID 33240817, 2020). "Furthermore, elevated levels of CD33+HLA-DR− myeloid cells were found in the tumor relative to normal mucosa, but not in the circulation when compared to healthy subjects." (PMID 32903466, 2020). "While total leucocyte infiltration level did not affect response to therapy, we did find a significant increase in immature CD33+HLA-DR− population tumor infiltration in non-responders (5.26 ± 1.23, n = 14) compared with responders (1.69 ± 0.35, n = 11, P = 0.02)." (PMID 32903466, 2020). "Notably, human BC samples in which SPARC was absent on tumor cells were also devoid of CD33+ cells expressing SPARC, in parallel with mouse results." (PMID 31281314, 2019). "This initial clinical work indicates that CD33-CAR-NK therapy may offer a new therapeutic option for R/R AML, which aims to reduce the tumor burden, eliminate LSCs, and provide opportunity to combine it with other therapies for more effective treatment of the R/R AML patients." (PMID 30400835, 2018). "Using major leukocyte lineage markers (CD3, CD4, CD8, CD66b, CD33, CD19, and CD56) we were able to determine using Ward’s minimum variance algorithm that leukocyte abundances and phenotypes determined from FNA samples largely are representative of the whole tumor." (PMID 27539742, 2016). "Using electroporation of CD33-specific CAR mRNA into human T cells, the authors are able to induce the transient expression of anti-CD33 CAR,118 which may confer clinically significant anti-tumor activity while avoiding long-term myelosuppression." (PMID 27367478, 2016). "In a similar way, CD33-specific ECAR modified T lymphocytes proved to efficiently eradicate AML cell lines in vitro independent of the antigen surface density and to release T cell cytokines upon encounter of target tumor cells similar to T cells engrafted with PSCA specific ECAR (data not shown)." (PMID 24699869, 2014). "In order to evaluate whether MDSCs belong to the tumor clone or normal residual cells, in 3 patients we analyzed BCR/ABL expression in both CD11b+CD33+CD14-HLADR- and CD14+HLADR- subpopulation cells and all samples showed the oncoprotein expression in both the two subsets (data not shown)." (PMID 25014230, 2014). "The density of CD8+ T cells and CD33+/p-STAT1+ cells was significantly correlated with patient vital status (p = 0.023, p < 0.001) and relapse occurrence (p = 0.005, p = 0.001); in addition, the high-density group of CD8+ T cells had a smaller tumor size (p = 0.005)." (PMID 23307253, 2013).